EGFR (epidermal growth factor receptor)
Diseases named in the same sentence as EGFR in open-access papers (continued):
Sharing a sentence is not in itself a finding about the gene and the disease.
prostate carcinoma (continued). "In EGFR-overexpressed prostate cancer cells, anandamide decreased EGFR levels by interacting with cannabinoid CB1 receptor, and consequently, inhibited the cancer cell proliferation." (PMID 32566240, 2020). "Of those, the “EGFR tyrosine kinase inhibitor resistance”, “prostate cancer” and, interestingly, “Tuberculosis” were shared in common with T2DM." (PMID 32956382, 2020). "EGFR reduces tumor suppressors and activates oncogenes to promote prostate cancer progression and bone metastasis." (PMID 33224867, 2020). "Hepatocytes have the ability to upregulate E-cadherin expression in tumor cells in prostate cancer liver metastasis, which seemed to be regulated by lowering epidermal growth factor receptor (EGFR) signaling." (PMID 33262947, 2020). "To further validate the specific interaction domain between WFDC2 and EGFR in prostate cancer, we divided EGFR into the extracellular domain EGFR-NT and the intracellular domain EGFR-NT." (PMID 32678075, 2020). "On the contrary, the combination of EGFR inhibitors and other drugs is becoming a promising treatment for refractory prostate cancer." (PMID 33224867, 2020). "Anomalous epidermal growth factor receptor (EGFR) signaling plays an important role in the progression of prostate cancer (PCa) and the transformation to castration-resistant PCa (CRPC)." (PMID 32328181, 2020). "Taken together, our findings suggest a crucial role played by FUT8 as a mediator in switching prostate cancer cells from nuclear receptor signaling (androgen receptor) to the cell surface receptor (EGFR) mechanisms in escaping castration-induced cell death." (PMID 32085441, 2020). "The tyrosine kinase inhibitor gefitinib inhibits epidermal growth factor receptor (EGFR) activation on MSCs by conditioned medium from PC3 prostate cancer cells (bone metastasis of prostate cancer), leading to decreased secretion of CCL5." (PMID 32630699, 2020). "The epidermal growth factor receptor (EGFR) was found to be a valuable target on prostate cancer (PCa) cells." (PMID 33260619, 2020). "Of note, EGFR, which is upregulated in African American breast and prostate cancers, appears to be a driver within this gene signature." (PMID 32414099, 2020). "Low-dose celecoxib combined with exisulind can affect the tumorigenesis of prostate cancer by regulating pathways such as EGFR, Akt, androgen receptor, and cyclin D1." (PMID 32913451, 2020). "In conclusion, our study identified that the tumor suppressor WFDC2 can suppress prostate cancer metastasis by inactivating EGFR signaling." (PMID 32678075, 2020). "In this study, we evaluated the role of FUT8, a glycosylated related enzyme as a master regulator to be involved in the transformation of prostate cancer cells from nuclear receptor AR-dependent signaling to the cell surface including the EGFR signaling." (PMID 32085441, 2020). "Since alpha 1-adrenoceptor antagonists have been reported to induce autophagy in prostate cancer cells and autophagy plays a role in resistance against EGFR-TKI, we examined if osimertinib and doxazosin induced autophagy in cancer cells and CSCs." (PMID 32764319, 2020). "Activation of EGFR by the epidermal growth factor (EGF) has been shown to promote prostate cancer growth, while suppressing the PSA production and secretion in the EGF stimulated cells." (PMID 32085441, 2020). "After demonstrating that WFDC2 inhibits the metastatic ability of prostate cancer by binding to the EGFR extracellular domain, we overexpressed WFDC2 and EGFR in PC-3 and DU-145 simultaneously." (PMID 32678075, 2020). "Transwell assay showed that EGFR can significantly rescue prostate cancer metastasis inhibited by WFDC2." (PMID 32678075, 2020). "In our in vitro data, we have demonstrated that overexpression of FUT8 was regulating the expression of EGFR in prostate cancer cells, which was responsible for the androgen-resistant mechanism." (PMID 32085441, 2020).
prostate carcinoma (continued). "Many studies indicate that EGFR is a potential therapeutic target for prostate cancer, especially for patients with CRPC." (PMID 33224867, 2020). "Several prostate cancer cell lines express functional EGFR and share a common vulnerability to EGFR inhibition in their proliferative and migratory ability." (PMID 32498343, 2020). "SPINK1 is similar on a structural point of view to EGF and activates the EGFR on the surface of prostate cancer cells, inducing their growth." (PMID 31366128, 2019). "These important findings provide a potential rational explanation for the disappointing efficacy of single agents that inhibit EGFR, such as erlotinib and gefitinib, in clinical trials of prostate cancer." (PMID 31649890, 2019). "Some evidences show that lycopene inhibits the expression of EGFR that is known to promote the survival, progression, and metastasis of prostate cancer." (PMID 31491956, 2019). "This is in line with previous observations that genetic knock-down or pharmacological inhibition of mPGES-1 increased the effect of the EGFR inhibitor erlotinib in prostate cancer cells in vitro and in vivo." (PMID 31231223, 2019). "Many other types of EGFR positive cancers, such as prostate cancer, and ovarian cancer are innately resistant to anti-EGFR mAbs." (PMID 31508364, 2019). "Our results provide evidence that overexpression of the EphB2 and Src signaling pathways regulate EGFR dynamics and cellular aggressiveness in some advanced prostate cancer cells." (PMID 31805710, 2019). "The most prominently involved pathways for the upregulated proteins were the viral process and ERBB2 signaling (GO) and EGFR tyrosine kinase inhibitor resistance as well as prostate cancer (KEGG)." (PMID 31323891, 2019). "Treatment with SMOi has been also shown to enhance the efficacy of EGFR inhibitors in non-small cell lung cancer, prostate cancer and glioblastoma CSCs." (PMID 31244888, 2019). "Apart from that, the role of EGFR/Erb-B2 receptor tyrosine kinase 2 (ERBB2) signaling in prostate cancer metastasis into the bone microenvironment has also been enumerated." (PMID 31137764, 2019). "We also assessed the effect of VM26 on the DU-145 prostate cancer cell line, characterized by an unusual decrease in EGFR level in response to EGF action in the autocrine loop, presumably associated with endocytosis." (PMID 31374910, 2019). "In prostate cancer cell lines, resveratrol reduced the levels of several receptor tyrosin kineses (EGFR, ErbB2/HER2, IGFR-1) in a time-dependent manner, particularly in androgen-negative prostate cancer cells." (PMID 30823649, 2019). "In prostate cancer cells, E-cadherin is mainly post-transcriptionally regulated wherein autocrine EGFR activation leads to catenin phosphorylation and junctional complexes instability and subsequent E-cadherin internalization and degradation." (PMID 31831069, 2019). "AR controls EGFR and ErbB2 expression in prostate cancer cells and in turn EGFR and ErbB2 concur to PCa progression activating AR signaling in hormone-poor conditions." (PMID 31816863, 2019). "Quercetin prevented epidermal growth factor (EGF)-induced EMT via the epidermal growth factor receptor /P13K/Akt/extracellular signal-regulated kinase 1/2 pathway and by suppressing transcription factors, Snail, Slug and Twist, in PC-3 prostate cancer cells." (PMID 30708951, 2019). "The compound VM26 demonstrates high protein degradation in EGFR-positive prostate cancer, which appears to be naturally tolerant to anti-EGFR therapy in clinical studies." (PMID 31374910, 2019). "We first surveyed a variety of prostate cancer cell lines and HeLa cells to gauge the effects of GlcN-induced inhibition of N-glycosylation (hereafter described as deglycosylation) on EGFR, a known glycosylated protein." (PMID 31618900, 2019). "Other recent studies have suggested an important role for EGFR in the propagation of populations of cancer stem cell like cells isolated from prostate cancer cell lines." (PMID 31366128, 2019).
prostate carcinoma (continued). "More importantly, the ethyl acetate extract of “Snow lotus” markedly reduced the phosphorylation of epidermal growth factor receptor, one of the therapy targets for prostate cancer." (PMID 32009958, 2019). "As advanced prostate cancer cells exhibit higher EGFR diffusivity, larger compartments of the plasma membrane, and loose cortical actin networks, we were interested in investigating the underlying molecular mechanisms for the differential actin organization." (PMID 31805710, 2019). "CRD domain of SP-D is known to interact with CD14, TLR-2, TLR-4, EGFR, and SIRPα that are reported to be present on prostate cancer cells and normal prostate tissues." (PMID 31355132, 2019). "Here, we show that SEMA3C is a secreted soluble autocrine growth factor that drives growth and treatment resistance of prostate cancer via activation of multiple RTKs such as EGFR, MET, and ErbB2 in a cognate ligand‐independent manner." (PMID 29348142, 2018). "EGFR signaling is involved in prostate cancer progression; however, single-agent therapy using an EGFR tyrosine kinase inhibitor (TKI) was ineffective in castration-resistant prostate cancer (CRPC)." (PMID 29455655, 2018). "We investigated the processes of TKI (AEE788)-induced autophagy, and autophagy induced by siRNA-mediated knockdown of EGFR protein on two types of cancer cells (prostate cancer PC3 cells and ovarian cancer SKOV3 cells)." (PMID 29358623, 2018). "In summary, this study identifies SEMA3C as a key secreted, autocrine growth factor that drives PCa growth and castration‐ and treatment‐resistant prostate cancer progression through activation of EGFR, HER2/ErbB2, MET, and c‐SRC tyrosine kinase pathways." (PMID 29348142, 2018). "EGR1 is known to function synergistically with NF-κB in upregulating IL-8 production in prostate cancer cells, and that its expression can be regulated by EGFR-integrin crosstalk." (PMID 29468142, 2018). "ETS variant gene 6 (ETV6) is a putative tumor suppressor and repressed by epidermal growth factor receptor (EGFR) signaling in prostate cancer." (PMID 29455655, 2018). "For prostate cancer cells, pAkt expression has a pivotal role in cell migration dependent of epidermal growth factor receptor (EGFR) by activating epithelial–mesenchymal transition." (PMID 29185464, 2017). "We also determined that the increased CXCR7 expression in prostate cancer cells during ADT enhances EGF-induced EGFR and ERK1/2 activation." (PMID 28596572, 2017). "It has been discovered that miR-133 and miR-146a suppress prostate cancer tumor progression via targeting EGFR, a tumour promoter for this disease." (PMID 28445135, 2017). "We demonstrated novel regulatory circuits involving miR-493-5p, c-Met, CREB1 and EGFR that controlled prostate cancer progression." (PMID 29137265, 2017). "A similar observation has also been reported in previous studies showing that the inhibited ERK activity promotes the EGFR activation and augments EGFR-driven motility of prostate cancer cells." (PMID 28057023, 2017). "Activation of the human epidermal growth factor receptor 1 (HER1) in prostate cancer contributes to metastatic progression as well as to disease relapse." (PMID 28539888, 2017). "Signaling through both the HGF/c-Met and EGF/EGFR is a potent inducer of cell scattering in the DU145 prostate cancer cell line." (PMID 28978320, 2017). "We examined decreased expression of CREB1 and EGFR in miR-493-5p-treated prostate cancer cells at both mRNA and protein level." (PMID 29137265, 2017). "Our study identified c-Met, CREB1, EGFR and miR-493-5p establish a regulatory loop in prostate cancer." (PMID 29137265, 2017). "Protein kinase C, alpha (PRKCA) mediates epidermal growth factor receptor transactivation in human prostate cancer cells." (PMID 28425476, 2017). "For example, overexpression of miR-143 was reported to suppress cell proliferation through regulating EGFR/RAS/MAPK pathway in prostate cancer cells." (PMID 28746466, 2017).
prostate carcinoma (continued). "Recently, direct targeting of EGFR by miR-146a was reported in castration-prostate cancer and HCC cells, leading to significant inhibition cell growth, colony formation, and migration in vitro." (PMID 28202053, 2017). "A recent interesting study on prostate cancer cells has shown that PTGES amplifies epidermal growth factor receptor-driven tumor progression and induces stemness and invasiveness." (PMID 29050246, 2017). "In LNCaP prostate cancer cells, EGFR was shown to induce Src interaction with AR through the proline-rich 372–379 region within the SH3 domain." (PMID 28671964, 2017). "In prostate cancer cells, CaSR stimulation transactivates the EGFR, leading to ERK phosphorylation and resultant PTHrP secretion." (PMID 28915604, 2017). "MST4 kinase activity is stimulated significantly by epidermal growth factor receptor (EGFR) ligands, which are known to promote the growth of prostate cancer cells." (PMID 26910843, 2016). "This modulation is especially important in tumors characterized by substantial over-expression of EGFR, including prostate cancer, in which the progression of the normal epithelium to an androgen-dependent tumor involves the activation of EGFR." (PMID 27187356, 2016). "The inverse correlation between endogenous ZNF216 and EGFR level of expression was also observed in prostate cancer cell lines, such as LNCaP, DU145 and PC3 cells." (PMID 27732953, 2016). "The correlation of upregulated δ-catenin and the activation of EGFR signaling in either human prostate tumor tissues or in vivo mouse models of prostate cancer, remains to be further investigated in future studies." (PMID 26883159, 2016). "In this study, we investigated the possible correlation between EGFR and δ-catenin in prostate cancer cells." (PMID 26883159, 2016). "The combination of EGFR inhibitor gefitinib and radiation has been reported to have promising activity against prostate cancer." (PMID 27611943, 2016). "These immunotoxins were tested in vitro and ex vivo against a panel of cancer types known to rely on EGFR signaling, including breast, epidermoid, pancreatic, and prostate cancers." (PMID 27153091, 2016). "Not only did our findings add a new perspective to the interaction of EGFR to the E-cadherin complex but they also provided novel insights into the roles of δ-catenin in prostate cancer cells." (PMID 26883159, 2016). "In prostate cancer, miR-574-3p was reported to regulate “Wnt signaling” to reduce cell proliferation by targeting epidermal growth factor receptor (EGFR) expression." (PMID 27565418, 2016). "Levels of EGFR immunoreactivity were increased in hormone-independent human prostate cancer cell lines." (PMID 27916908, 2016). "The histology results indicate that PSEP enables the knockdown of EGFR and survivin and induces tumor cell apoptosis in vivo, which is translated into a significant suppression of tumor growth in xenograft prostate cancer." (PMID 27456457, 2016). "PD168393, an inhibitor of EGFR, potentiates cytotoxic effect of taxol against prostate cancer cells." (PMID 26863629, 2016). "Here, we reported that EGFR co-localized and interacted with δ-catenin in prostate cancer cells, adding a brand new perspective to the interaction of EGFR to the E-cadherin complex." (PMID 26883159, 2016). "Simultaneous blockade of Hh and EGFR signaling inhibited proliferation and induced apoptosis, and improved the cytotoxic effects of docetaxel in metastatic prostate cancer cells." (PMID 26943330, 2016). "In conclusion, our study suggests that miR-3622b plays a tumor suppressive role and is frequently downregulated in prostate cancer, leading to EGFR upregulation." (PMID 27611943, 2016). "Monoclonal antibody against EGFR has gained an effective improvement in patients with prostate cancer." (PMID 26182292, 2015). "One such overexpressed protein, in African American prostate cancer patients, is the epidermal growth factor receptor, EGFR." (PMID 25802834, 2015).
prostate carcinoma (continued). "In PC3 prostate cancer cells, NT activates proliferation through EGFR transactivation in a PKC (protein kinase C, PKC)-dependent pathway." (PMID 26215716, 2015). "Curcumin suppressed EGFR signaling in prostate cancer cells by inhibiting ligand-induced activation of EGFR and its intrinsic tyrosine kinase activity." (PMID 25665066, 2015). "Signaling through the epidermal growth factor (EGF) and its family of receptors (i.e., EGFR, HER2/Neu, erbB3, and erbB4) has also been implicated in the growth and progression of prostate cancer." (PMID 26566796, 2015). "Our results showed that ATP stimulation resulted in activation of EGFR (Tyr-1068) in prostate cancer cells." (PMID 26182292, 2015). "In prostate cancer cells, co-inhibition of epidermal growth factor receptor and IGF-1R reduced phosphorylation of IRS-1 and its interaction with RAD51, suppressing HR and increasing radio-sensitivity." (PMID 26510816, 2015). "It has been reported that direct activation of the cannabinoid CB1 receptor in epidermal growth factor (EGR)-stimulated PC-3 prostate cancer cells results in an anti-proliferative effect accompanied by a down-regulation of EGF receptors (EGFR)." (PMID 25012825, 2014). "More importantly, EGFR expression increased as prostate cancer progressed from an androgen-dependent to an androgen-independent stage." (PMID 24741584, 2014). "A loss of expression of AR was noted in these cells (data not shown), which supports the report showing an inverse relationship between expression of AR and EGFR in prostate cancer patients." (PMID 24387052, 2014). "AEA inhibits the proliferation of human prostate cancer cell lines by downregulating epidermal growth factor receptor." (PMID 24699635, 2014). "Overexpression of AGK transactivates epidermal growth factor receptor (EGFR) and enhances the proliferation and migration of prostate cancer cells in vitro." (PMID 25474138, 2014). "Concerning on pathway enrichment analysis, Transcription Androgen Receptor (AR) nuclear signaling and Epidermal Growth Factor Receptor (EGFR) signalling pathway were clearly shown to be the pathway targets for prostate cancer progression." (PMID 25080090, 2014). "MiR-133 and miR-146a have also been shown to target EGFR and to produce similar anti-proliferative, anti-migratory effects in androgen-insensitive prostate cancer cell lines in vitro." (PMID 25496077, 2014). "Many studies confirmed that overexpression of EGFR contributes significantly to the progression of prostate cancer." (PMID 24741584, 2014). "Epidermal growth factor receptor (EGFR) is a critical signaling molecule that controls several signaling pathways in prostate cancer." (PMID 25004126, 2014). "Erlotinib, a selective tyrosine kinase inhibitor for EGFR, have reported benefits prostate cancer patients in clinical studies." (PMID 25551444, 2014). "But experiments would be desirable to further clarify the relationship between Gαs and EGFR and identify their function in the progression of prostate cancer." (PMID 24741584, 2014). "Erlotinib, the first-generation EGFR inhibitor, has single-agent activity against various cancer cells, including prostate cancer." (PMID 25551444, 2014). "MiR-133 inhibits cell proliferation, migration and invasion in prostate cancer cells by targeting EGFR." (PMID 25594007, 2014). "Among these modules, transcription Androgen Receptor (AR) nuclear signaling and Epidermal Growth Factor Receptor (EGFR) signalling pathway were shown to be the pathway targets for prostate cancer progression." (PMID 25080090, 2014). "Markedly, our data demonstrate that the activated EGFR signaling-induced autocrine AREG, EREG, and TGFA expression in Ras-mutated prostate cancer cells is associated with a down-regulation in miR-203 expression level in an EGF-dependent manner." (PMID 25004126, 2014).